TERT (telomerase reverse transcriptase)
Diseases named in the same sentence as TERT in open-access papers (continued):
Sharing a sentence is not in itself a finding about the gene and the disease.
lymph node metastasis (continued). "Mutated genes associated with lymph node metastasis in the univariate analysis, including RET, ATM, PIK3CA, TERT, GGT1 and fusions, were incorporated to construct a gene signature model." (PMID 38886866, 2024). "Lymph node metastases with BRAF and TERT promoter mutations were found to exhibit lower iodine avidity, with differences higher than previously reported." (PMID 37352166, 2023). "Extrathyroidal extension, lymph node metastasis, AJCC stage, TERT promoter mutation, and NIS expression status were associated with recurrence-free survival in univariate analysis." (PMID 35723359, 2022). "RAS mutations were prevalent in the follicular variant, TERT in older patients, and RET/PTC in patients with lymph node metastasis (all significant after the multiple-comparison correction)." (PMID 32425887, 2020). "Our findings illustrated that TERT promoter mutations were more likely to be present in patients with larger tumors, stage III or IV disease, lymph node metastasis, and distant metastasis." (PMID 27833153, 2016). "Previous studies have also reported that the TERT MNS16A polymorphism was associated with clinical progression in some types of cancer, including clinical stage, tumor stage, lymph-node metastasis and survival time, although the results were contradictory." (PMID 21929825, 2011). "Furthermore, patients displaying a TERT amplification were more likely to have lymph node metastases (p = 0.018)." (PMID 37848472, 2023). "The lateral lymph node metastasis rate in this group of patients is also high (70%, 7/10), and they can be classified as a high-risk group clinically, but other clinical characteristics are significantly different from the BRAF+TERT group of patients." (PMID 35865459, 2022). "Lymph node metastasis was present in 115 (57.8%) of 199 patients with TERT promoter mutations and in 869 (47.0%) of 1849 patients without TERT promoter mutations." (PMID 27833153, 2016). "According to our analysis, lymph node metastasis occurred more frequently in patients with TERT promoter mutations than in those without TERT promoter mutations (P = 0.02)." (PMID 27833153, 2016). "The multivariable modelling showed that tumour tissue localisation (primary tumour or lymph node metastasis), histological subtype, TPO and NIS expression and TERT promoter mutation were each independent predictors of iodine avidity that could explain 68% of the observed variation of iodine avidity." (PMID 37352166, 2023). "In addition to the traditional clinicopathological risk factors, specific molecular profiles (e.g., BRAF, TERT, and RET) may be used to predict the risk of extrathyroidal extension and lymph node metastases." (PMID 33392186, 2020). "Other factors like FAT3, APC, PTPRD (P = 0.01), lymph-node metastasis, EPHA3, TERT, and STK11 (P = 0.05) that have been found to be related to TMB distribution." (PMID 33996530, 2020). "In patients with NPC, increased telomerase activity and TERT expression was seen more frequently in patients with advanced clinical stage (III to IV) and lymph-node metastasis (N1 to N3)." (PMID 21929825, 2011). "Our data indicate that TERT expression is not involved in the development early lymph node metastasis in patients with sub-centimetric PTC." (PMID 38616265, 2024).
urothelial carcinoma (33 papers, 2014 to 2026). A malignant neoplasm derived from the transitional epithelium of the urinary tract (urinary bladder, ureter, urethra, or renal pelvis). "Hotspot mutations in the FGFR3 gene (R248C, S249F/C, G372C, and Y375C (missense gain-of-function mutations)) and upstream of the TERT promoter (C228T and C250T (gain-of-function mutations)) are often identified in urothelial carcinoma samples." (PMID 40722489, 2025). "Telomerase reverse transcriptase (TERT) mutation represents the most prevalent genetic mutation found in urothelial carcinoma (UC) and holds potential as a prognostic indicator for tumor outcomes." (PMID 37915019, 2023). "Telomerase reverse transcriptase (TERT) promoter mutations are frequently found in tumors or urine from patients with urothelial carcinoma (UC)." (PMID 32533903, 2020). "TERT promoter mutations are shown to be tightly associated with the presence of FGFR3 mutations in urothelial carcinomas (UC)." (PMID 28416747, 2017). "TERT promoter mutations, originally discovered in ~70% of melanomas, have also been found to be the most common form of genetic mutations in urothelial carcinomas." (PMID 25937998, 2015). "Subsequently, several malignancies including urothelial carcinoma were also found to be associated with the same TERT promoter mutations." (PMID 25042800, 2014). "In our study, it was found that the hot spot mutations of TERT promoter were related to malignant urinary epithelial lesions, and they played an auxiliary role in the diagnosis of urothelial carcinoma, but they were of little significance in the diagnosis of UBC pathological grade." (PMID 33854611, 2021). "A recent pan-cancer study which included sequencing of n = 796 urothelial cancers confirmed high frequencies (>70%) of TERT promoter mutations in urothelial carcinomas of the urinary bladder and the urethra and a slightly reduced prevalence in upper tract urothelial cancers (53%)." (PMID 34200508, 2021). "Despite the frequent occurrence of TERT promoter mutations in urothelial carcinoma, the incidence of the mutations in SCC of the urinary bladder is unknown." (PMID 25042800, 2014). "Also, MBTs lack TERT promoter mutations, commonly found in urothelial carcinoma." (PMID 38539441, 2024). "Uromonitor® is a quantitative PCR-based assay targeting hotspot variants in the TERT promoter, FGFR3, and KRAS, which are frequently altered in urothelial carcinoma." (PMID 42193009, 2026). "TERT promoter hypermethylation, a common finding in cancerous tissues and urothelial carcinomas expressing TERT, offers a distinct pathway compared to the conventional suppression of gene expression." (PMID 38891848, 2024). "Upregulation of TERT expression and resulting telomerase activity occurs in the large majority of malignancies, including urothelial carcinoma." (PMID 34127009, 2021). "Likewise, TERT promoter methylation can be monitored in liquid biopsies from patients with urothelial carcinomas." (PMID 39760332, 2025). "In addition, although TERT showed clinically relevant values in urothelial carcinoma, a rapid and cost-effective method needs to be developed before routine use." (PMID 37915019, 2023). "Multiple studies, including our unpublished results, demonstrated that up to 70-80% of urothelial carcinoma carries the TERT promoter mutations irrespective of grade, stage or location." (PMID 25937998, 2015). "In addition, they showed that analysis of urinary DNA TERT promoter hotspots after TURBT could be used as a marker for recurrent urothelial carcinoma." (PMID 31803629, 2019).
urothelial carcinoma (continued). "In another study, this combination decreased TERT promoter activity, as assessed by luciferase activity, in urothelial carcinoma cell lines (T24 cell line and CLS-439 cell line), thereby showing that rs2853669 may modulate the TERT promoter activity in a cell type-specific manner." (PMID 26575952, 2016).
gastric cancer (31 papers, 2003 to 2025). A primary or metastatic malignant neoplasm involving the stomach. "In gastric cancer, TERT promoter mutation is a rare event, and TERT expression is observed in gastric epithelium with markedly decreased telomeres." (PMID 36834592, 2023). "Recently, a study has suggested that rs2736100 polymorphism regulated TERT expression and telomere length in gastric cancer patients." (PMID 32694935, 2020). "Up to now, numbers of studies have discussed association between TERT gene SNPs and the risks of various cancers, including breast, lung, colorectal, ovarian, prostate, and gastric cancers." (PMID 32694935, 2020). "The rs2736100 T > G polymorphism in the second intron of the TERT gene has been associated with shortened telomere length in gastric cancer." (PMID 28418878, 2017). "Since then, TERT variants have been associated with various cancers, including breast, lung, colorectal, ovarian, prostate, and gastric cancers." (PMID 28418878, 2017). "In this study, we validated the association between TERT polymorphisms and gastric cancer (GC) risk with a case-control study in a Chinese Han population." (PMID 27825130, 2016). "This suggests that the repeated regeneration and proliferation associated with H. pylori infection in gastric cancer may cause telomere shortening, resulting in induction of TERT expression, telomerase activation, and an increase in stem cells." (PMID 36834592, 2023). "However, only 1% of gastric cancers reported to date have been shown to carry TERT promoter mutations." (PMID 36834592, 2023). "Current evidence presents that the rs10069690 T allele can trigger the development of the coproduction of full-length TERT and an alternatively spliced by creating splice donor site in intron 4 of TERT, which may increase gastric cancer risk by reducing telomerase activity and telomere shortening." (PMID 35847915, 2022). "Secondly, deletions or rearrangements occur at the EBF1 binding site proximal to the TERT promoter in gastric cancer cells." (PMID 39871386, 2025). "Among the Fujian cohort mutations classified as metastatic markers in gastric carcinomas, one is a PTPRT mutation, and another, Chondrosarcoma TERT promoter mutation is a metastasis marker." (PMID 40758706, 2025). "Telomere shortening and telomerase reverse transcriptase (TERT) activation are frequently observed in gastric cancer and are considered to be early events in carcinogenesis of the gastric mucosa." (PMID 36834592, 2023). "Another study also suggested the feasibility of stool TERT promoter methylation analyses for the non-invasive screening of gastric cancer." (PMID 35309131, 2022). "For example, studies have demonstrated that TERT is highly expressed in gastric cancer tissues and is related to lymph node metastasis." (PMID 34482792, 2021). "A Brazilian study investigated the expression of telomerase reverse transcriptase (TERT) gene mRNA in normal gastric mucosa, precancerous gastric lesions, and gastric cancer." (PMID 34071181, 2021). "Slightly elevated levels of TERT mRNA and protein were also reported in 45 to 50% of intestinal metaplasia and gastric ulcer cases, and 79% of gastric cancer showed higher TERT levels." (PMID 32082377, 2019). "miR-1266 was downregulated in gastric cancer tissues and was shown to inhibit tumor growth and invasion by targeting telomerase reverse transcriptase (hTERT), while miR-3678 was found to be significantly downregulated in lymphatic metastases." (PMID 26472042, 2015). "In gastric cancer samples, not only is the frequency of TERT promoter methylation significantly higher than in normal gastric mucosa, but 80% of these cancer samples also exhibit TERT expression." (PMID 39871386, 2025). "To further determine whether the regulation of GABPA binding capacity by Sp1 depends on the TERT promoter mutations, we knocked down Sp1 in gastric cancer cell line AGS and colon cancer cell line RKO carrying BRAFV600E mutation and wild-type TERT promoter." (PMID 33483600, 2021).
gastric cancer (continued). "It is during later stages of carcinogenesis that the activation of TERT expression and telomerase activity may occur, resulting in an uncontrolled proliferation pattern and tumorigenesis, previously reported in gastric cancer." (PMID 32082377, 2019). "TERT has been reported to promote epithelial-mesenchymal transition in gastric cancer cells." (PMID 24334332, 2013). "The sensitivity and specificity of a single marker for gastric cancer detection in the training set for SDC2 were 40.9 and 93.3%, for TERT were 36.4 and 90.0%, for RASSF2 were 31.8 and 93.3%, for SFRP2 were 22.7 and 90.0%, and for Hb were 27.3 and 90.0%." (PMID 35309131, 2022). "As an example, overexpressed miR-1182 could suppress telomerase reverse transcriptase (hTERT) expression and proliferation and invasion in gastric cancer (GC) cells." (PMID 33750398, 2021). "Regarding miRNAs that targeted the TERT gene, the hsa-miR-874-3p has not been described in PTC, although its suppressed expression has been associated with several human solid tumor prognosis, such as osteosarcoma and gastric carcinoma." (PMID 37569841, 2023). "The results showed that the methylation of SDC2, SFRP2, TERT, and RASSF2 has a certain sensitivity and high specificity in GC screening, which is a potential fecal biomarker of gastric cancer." (PMID 35309131, 2022).
non-small cell lung carcinoma (31 papers, 2007 to 2025). A group of at least three distinct histological types of lung cancer, including non-small cell squamous cell carcinoma, adenocarcinoma, and large cell carcinoma. "In this study, we measured TERT splice variant expression and telomerase activity in induced pluripotent stem cells (iPSCs), neural progenitor cells (NPCs), and non-small cell lung cancer cells (NSCLC, Calu-6 cells)." (PMID 37531400, 2023). "The results of this study suggested that rs2853677 of TERT signifies association in multiple cancers and suggests that it can become potential marker for diagnosis of non-small cell lung cancer and leukemia." (PMID 31126249, 2019). "We observed that the genetic variant rs2853677 in the TERT loci is linked with an increased non-small cell lung cancer and leukemia risk in Jammu and Kashmir (North Indian) population." (PMID 31126249, 2019). "In the present study, we conducted an association study of variant rs2853677 of TERT gene and susceptibility to non-small cell lung carcinoma and leukemia in population of Jammu and Kashmir." (PMID 31126249, 2019). "TERT −244T>C was noted to have increased telomerase activity related to the T allele in a recent study of non-small cell lung cancer." (PMID 17848914, 2007). "This study assessed the association between the TERT gene and non-small cell lung carcinoma (NSCLC) in Iraq." (PMID 38084250, 2023). "Furthermore, TERT copy number alterations in solitary fibrous tumors and TERT mutations in non-small cell lung cancer could be associated with a higher risk of metastasis." (PMID 37848472, 2023). "The expression of inflammatory markers INFγ, TNF, IL10 and PD-1 in a non-small-cell lung cancer mouse model was influenced by TERT." (PMID 39858033, 2025). "UCPVax, a therapeutic cancer vaccine composed of two distinct peptides from human telomerase reverse transcriptase (TERT), has shown safety and the ability to stimulate an immune reaction in non-small cell lung cancer trials (NCT02818426)." (PMID 38816668, 2024). "We have previously shown that when PTBP1 is knocked down, FL TERT and telomerase levels are reduced in non-small cell lung cancer (NSCLC) cells." (PMID 37531400, 2023). "As TERT is commonly over-expressed and mutated in multiple human cancers, here we first explored genomic alterations in the TERT locus and their correlation with survival in non-small cell lung cancer (NSCLC) patients." (PMID 37085672, 2023). "Vorinostat downregulated TERT and repressed telomerase activity in non-small cell lung cancer and lymphoma cells." (PMID 33802026, 2021). "For example, spontaneous Th1 responses against the telomerase reverse transcriptase (TERT) antigen are observed in approximately one-third of patients with non-small cell lung carcinoma (NSCLC, preferentially at localized stage)." (PMID 33546283, 2021). "Our result revealed the complex genetic regulation of telomere genetics and highlighted the critical role of telomere maintenance gene (TERT) in the pathogenesis of non-small cell lung cancer and leukemia." (PMID 31126249, 2019). "Significant discrepancies between TERT mRNA expression and telomerase activity have also been identified in soft tissue sarcomas and non-small cell lung cancer." (PMID 24752326, 2014). "The gain at chromosomal region 5p15.33, containing TERT, is one of the most frequent genetic events in early stages of non-small-cell lung cancer." (PMID 24260099, 2013). "A higher anti-TERT Th1 response and low expression of PD-1+ T cell immunoglobulin (Ig) mucin-3 (TIM-3)+ CD4+ T exhausted cells are associated with better patient prognosis in non-small cell lung cancer (NSCLC)." (PMID 38328405, 2023).
non-small cell lung carcinoma (continued). "The cancer vaccine, GV1001, a TERT derived peptide for telomerase driven immunotherapy is involved in several clinical trials in non-small cell lung cancer (NSCLC), pancreatic cancer, hepatocellular carcinoma and malignant melanoma, where few side effects have been reported." (PMID 27657809, 2017). "For example, recently NOVA1 was reported to be an important regulator of TERT alternative splicing in non-small cell lung carcinoma (NSCLC)." (PMID 32674474, 2020). "In our cohort of patients presenting predominantly with a non-small cell lung cancer (NSCLC), we found that T-cell responses against TERT were naturally present in 46% of the cases." (PMID 34144673, 2021). "In non-small cell lung cancer cell lines, EGF has been reported to activate TERT transcription by inducing direct binding of ETS2 and Myc/Max to the TERT promoter." (PMID 28184371, 2017).